RNU6-1314P (RNA, U6 small nuclear 1314, pseudogene)
Gene: Small nuclear RNA gene on chromosome Y (26,360,989 to 26,361,092, forward strand). Ensembl gene ENSG00000252948.
Homologues: Orthologues: macaque U6 (95% identical), mouse Gm22281 (79% identical), dog U6 (77% identical), guinea pig U6 (76% identical), rabbit U6 (75% identical), rat LOC120095360 (75% identical). Paralogues in human: RNU6-89P (93% identical), RNU6-38P (90% identical), RNU6-15P (89% identical), RNU6-1145P (88% identical), RNU6-20P (88% identical), RNU6-29P (88% identical), RNU6-574P (88% identical), RNU6-639P (88% identical), RNU6-1 (88% identical), RNU6-1011P (88% identical), RNU6-166P (88% identical), RNU6-2 (88% identical), and 1290 more.